MCUR1 (mitochondrial calcium uniporter regulator 1)
Description:
Key regulator of mitochondrial calcium uniporter (MCU) required for calcium entry into mitochondrion. Plays a direct role in uniporter-mediated calcium uptake via a direct interaction with MCU. Probably involved in the assembly of the membrane components of the uniporter complex (uniplex).
Synonyms: C6orf79; CCDC90A; FLJ20958; FMP32
Tractability: Antibody: UniProt predicts a signal peptide or a membrane-spanning region. PROTAC: ubiquitination databases record sites on it; its protein half-life has been measured.
Gene: Protein-coding gene on chromosome 6 (13,786,557 to 13,814,696, reverse strand). Ensembl gene ENSG00000050393.
Subcellular location: Mitochondrion inner membrane
Gene Ontology:
Molecular function: protein binding; protein-macromolecule adaptor activity; protein-containing complex binding
Biological process: calcium import into the mitochondrion; calcium ion import; mitochondrial calcium ion transmembrane transport; positive regulation of mitochondrial calcium ion concentration
Cellular component: mitochondrial inner membrane; mitochondrion
Genetic constraint (gnomAD): Loss-of-function variants: 18 observed, 20.01 expected, observed/expected ratio (o/e) 0.9, 90% interval 0.62 to 1.33. The synonymous counts are far from expectation, so gnomAD's model fits this gene poorly and the ratio says little. Missense variants: 350 observed, 272.92 expected, observed/expected ratio (o/e) 1.28, 90% interval 1.17 to 1.4. Synonymous variants: 178 observed, 117.34 expected, observed/expected ratio (o/e) 1.52, 90% interval 1.34 to 1.72.
Homologues: Orthologues: chimpanzee MCUR1 (99% identical), macaque MCUR1 (83% identical), pig MCUR1 (79% identical), rat Mcur1 (70% identical), mouse Mcur1 (69% identical), dog MCUR1 (69% identical), guinea pig MCUR1 (59% identical), rabbit MCUR1 (53% identical), tropical clawed frog mcur1 (45% identical), zebrafish mcur1 (41% identical). Paralogues in human: CCDC90B (34% identical).
Diseases named in the same sentence as MCUR1 in open-access papers:
MCUR1 is named in the same sentence as 13 diseases in open-access papers, as found by Europe PMC text mining. Sharing a sentence is not in itself a finding about the gene and the disease. The quoted sentences say what the papers report.
hepatocellular carcinoma (7 papers, 2019 to 2023). A malignant tumor that arises from hepatocytes. "In fact, the expression of the mitochondrial calcium uniporter regulator 1 (MCUR1) was reported to be higher in hepatocellular carcinoma (HCC) with metastasis and associated with tumour progression." (PMID 36701089, 2023). "MCUR1 facilitates epithelial-mesenchymal transition and metastasis in hepatocellular carcinoma involved via the mitochondrial calcium dependent ROS/Nrf2/Notch pathway, however, no relevant literature has been reported to date in diabetic retinopathy." (PMID 34603851, 2021). "Jin and his colleagues observed that MCUR1 (Mitochondrial Calcium Uniporter Regulator 1) is up-regulated in hepatocellular carcinoma (HCC) which promotes EMT by activating ROS/Notch1/Nrf2 pathways." (PMID 31766246, 2019). "Up-regulated expression of MCUR1 was observed in a pathological condition: MCUR1 promoted the epithelial-mesenchymal transition of hepatocellular carcinoma cells followed by invasion and metastasis." (PMID 31569359, 2019). "In this context, MCUR1-dependent mitochondrial Ca2+ uptake has been reported to stimulate in vitro invasion and in vivo metastasis by promoting EMT via the ROS/Nrf2/Notch pathway and Snail transcription, pointing to MCUR1 as a potential therapeutic target for hepatocellular carcinoma treatment." (PMID 34071006, 2021). "Additionally, MCUR1-mediated mitochondrial Ca2+ signaling was reported to facilitate cell survival of hepatocellular carcinoma (HCC) upon pro-apoptotic stimuli." (PMID 35851420, 2022). "Interestingly, recent evidence of a possible implication of MCUR1 in human pathology has been provided in the hepatocellular carcinoma cell (HCC) model." (PMID 34071006, 2021). "Moreover, the in vitro and in vivo experiments also first demonstrated that MCUR1-induced mitochondrial Ca2+ uptake activated the ROS/Nrf2/Notch signaling and thus facilitated the epithelial-mesenchymal transition and metastasis in hepatocellular carcinoma." (PMID 30909929, 2019).
Hyperglycaemia (1 paper, 2017). "To conclude, our study suggests that hyperglycaemia results in enhanced expression of MCU and MCUR1, leading to mitochondrial Ca2+ overload." (PMID 28777009, 2017).
periodontitis (1 paper, 2024). An acute or chronic inflammatory process that affects the tissues that surround and support the teeth. "The integration of GWAS with the expression quantitative trait locis of these genes from the peripheral blood genetically prioritized 6 candidate genes, including 2 risk genes (RAP2A, MCUR1) and 4 protective genes (WNK1, NFIX, FOS, PANX1) in periodontitis-related T2D." (PMID 38811930, 2024). "Findings from the MR and scRNA-seq of the current study suggested that the evaluated expression of MCUR1 in platelets from PBMCs contributed to the pathogenesis of periodontitis-related T2D, indicating the key roles of mitochondrial dysfunction in promoting T2D." (PMID 38811930, 2024). "The integration of GWAS with the eQTLs of these genes from the peripheral blood prioritized 6 genes, including MCUR1, RAP2A, FOS, PANX1, NFIX and WNK1, in the pathogenesis of periodontitis-related T2D." (PMID 38811930, 2024). "MCUR1, RAP2A, FOS, PANX1, NFIX and WNK1 may play important roles in the pathogenesis of periodontitis-related T2D, shedding light on the development of potential drug targets." (PMID 38811930, 2024). "Furthermore, MCUR1, RAP2A, FOS, PANX1, NFIX and WNK1 were verified to play important roles in the pathogenesis of periodontitis-related T2D, shedding light on the discovery of potential drug targets for periodontitis patients to prevent T2D." (PMID 38811930, 2024).
tumor (7 papers, 2019 to 2023). "MCUR1 expression was significantly higher in HCC with metastasis and associated with tumor progression." (PMID 30909929, 2019). "More importantly, we provided the first evidence indicating high MCUR1 expression in HCC tissues with metastasis and significant association between MCUR1 expression and tumor progression in HCC patients." (PMID 30909929, 2019). "To evaluate the role of MCUR1 in tumor EMT and metastasis in vivo, we established the orthotopic transplantation model of HCC metastasis in nude mice." (PMID 30909929, 2019). "Finally, RT-qPCR experiments revealed that after DOX/sh-1@PLT treatment, the expression of circ_0000098 and MCUR1 in tumor tissues was decreased, whereas miR-383 expression was induced in tumor tissues." (PMID 36071480, 2022). "MCUR1 upregulation promotes tumour proliferation and apoptosis avoidance, but also facilitates epithelial–mesenchymal transition (EMT) and metastatic capacity via the ROS/nuclear factor erythroid 2-related factor 2 (Nrf2)/Notch1 pathway in HCC, in both in vitro and in vivo models." (PMID 35269437, 2022). "Similarly, expression of the MCU regulator mitochondrial calcium uniporter regulator 1 (MCUR1) stimulates ROS-mediated cancer cell migration and survival, accelerating tumor growth." (PMID 33282859, 2020). "MCUR1 and MICU1 also influenced patients' prognosis and tumor occurrence and progression." (PMID 37056383, 2023). "MCUR1-overexpressed MHCC97H cell lines and xenograft tumours display higher growth capacity." (PMID 35269437, 2022). "Therefore, the use of PLTs to entrap MCUR1 inhibitors in HCC therapy is of great interest, as it may effectively reduce MDR in tumor tissue, resulting in a better therapeutic outcome." (PMID 36071480, 2022).
cancer (3 papers, 2019 to 2022). A tumor composed of atypical neoplastic, often pleomorphic cells that invade other tissues. "In addition, we hypothesized that circ_0000098 might influence anti-cancer drug efflux through the miR-383/MCUR1 axis." (PMID 36071480, 2022). "And the content of hsa_circ_0000098 was higher in DOX-resistant patients.The findings indicated that dysregulation of the circ_0000098/miR-383/MCUR1 signaling pathway leads to P-gp overexpression and elevated ATP levels, both of which may promote anti-cancer drug efflux and chemoresistance in HCC." (PMID 36071480, 2022). "Mitochondrial calcium uniporter regulator 1 (MCUR1) has been shown to be frequently upregulated in HCC and promote cancer cell survival." (PMID 30909929, 2019). "Mitochondrial calcium uniporter regulator 1 (MCUR1) functions as a scaffold factor by binding to mitochondrial calcium uniporter (MCU) and essential MCU regulator (EMRE), and plays a crucial role in mitochondrial Ca2+ absorption and ATP production in cancer cells." (PMID 36071480, 2022).
myopathies (1 paper, 2018). "Of note, muscle biopsies also showed up-regulation of members of the mitochondrial Ca2+ uptake machinery (MCU, MCUR1), indicating that increased mitochondrial Ca2+ uptake might also happen in vivo, as part of the pathological process in core myopathies." (PMID 29701772, 2018).
MCUR1 also shares sentences with these, for which no sentence is quoted: ovarian carcinoma (2 papers); breast carcinoma (1); cognitive decline (1); colorectal adenocarcinoma (1); diabetes (1); diabetic retinopathy (1); vacuolar myopathy (1).